HGF (hepatocyte growth factor)
Diseases named in the same sentence as HGF in open-access papers (continued):
Sharing a sentence is not in itself a finding about the gene and the disease.
tumor (continued). "Other authors have reported that tumor cell-derived IL1α induces HGF secretion by CAFs, enhancing in turn the metastatic potential of tumor cells." (PMID 34066976, 2021). "HGF/c-Met signaling has been reported to be involved in tumor metastasis by activating its downstream effector components." (PMID 34848680, 2021). "Free anti-PD-L1 antibodies exhibited limited inhibition to the tumor growth; however, its combination with HGF reversed the infaust situation completely." (PMID 34593794, 2021). "In our previous work, our group identified hepatocyte growth factor activator inhibitor type-1 (HAI-1) as a cell-autonomous tumor suppressor that negatively regulates the HGF pathway." (PMID 34185790, 2021). "In cancer cells, abnormal HGF/C-MET axis promoted tumor progression by inducing PI3K/AKT, Ras/MAPK and other signaling pathways." (PMID 34249078, 2021). "Our data indicate that HGF secreted by the activated stroma induces MET activation in tumor cells, and these respond by increasing TNC secretion." (PMID 34298732, 2021). "PDAC is characterised by a strong tumour stromal proliferative response, and the HGF/MET pathway is involved in the signal transmission interaction between tumour and stromal cells." (PMID 33816276, 2021). "Emerging evidence has indicated that HGF/MET signaling plays a crucial role on tumor formation, development, maintenance, metastasis as well as the efficacy to systemic therapy, including sorafenib, in HCC 3, 6, 8, 34-36." (PMID 33500715, 2021). "Accordingly, the immunohistochemical evaluation revealed that HGF derived from GCMSCs promoted tumor angiogenesis." (PMID 33718248, 2021). "This impact of c‐MET on EMT has a drastic impact on cancer cell invasiveness and metastatic abilities, and is reflected in the upregulation of both c‐MET and HGF in circulating tumor cells (CTCs), as shown, for example, in hepatocellular carcinoma." (PMID 34542930, 2021). "Consistently, cells cultured from EphA2-knockout KPC tumours (KPC-PDAC cells) display profoundly reduced ability to invade into Matrigel towards a gradient of HGF." (PMID 34819513, 2021). "Within the TME, these cells can then differentiate into tumor-associated macrophages (TAMs) and tumor-associated neutrophils (TANs) and release several important endothelial factors and growth factors such as VEGF, HGF, MMPs, and various interleukins." (PMID 33808627, 2021). "Among these inducers of EMT, which can be also released by the tumor cell, there are growth factors such as the transforming growth factor β (TGFβ) and the hepatocyte growth factor (HGF), as well as cytokines, which include the tumor necrosis factor α (TNFα)." (PMID 34830097, 2021). "Taken together, these results suggest that the addition of merestinib to abemaciclib enhances the suppression of UM growth in the tumor microenvironment where human HGF is produced." (PMID 33806615, 2021). "Conversely, the two major adipokines, adiponectin and leptin, as well as some growth factors (EGF, VEGF-α and HGF) seemed to play a major role in the tissue crosstalk around the tumour." (PMID 32472095, 2020). "Here, soluble HGF was correlated with tumor cMet (r = 0.62, p = 0.056), HGF (r = 0.54, p = 0.106) and the cMet–HGF complex (r = 0.65, p = 0.044) and soluble cMet was correlated with the cMet–HGF complex (r = 0.58, p = 0.0677)." (PMID 32545260, 2020). "HGF overexpression further affects the activation of MET and its downstream signaling pathways, thereby causing tumor resistance to MET inhibitors." (PMID 32435640, 2020). "Study of the c-Met-HGF axis in non-small cell lung cancer (NSCLC) has focused on the roles of c-MET signaling in neoplastic epithelial cells and the secretion of its ligand hepatocyte growth factor (HGF) by tumor stromal cells." (PMID 32117721, 2020).
tumor (continued). "Platelets can mediate tumor cell growth, angiogenesis, and proliferation by releasing vascular endothelial growth factor, hepatocyte growth factor, basic fibroblast growth factor, and angiopoietin-1, as well as other angiogenesis and tumor growth factors." (PMID 33363021, 2020). "Dysregulation of HSPG-regulated HGF/c-MET signaling in tumor microenvironment plays a key role in hepatocarcinoma." (PMID 32916872, 2020). "One week after the impantation of cells, when tumours had formed in the pancreas, mice were treated with the HGF neutralising antibody, AMG102 (Rilotumumab)." (PMID 33271944, 2020). "We aimed to explore the tumor expression of HGF, c-MET, CXCL12, and CXCR4 and their correlation with patient overall survival (OS)." (PMID 32188473, 2020). "Macrophages not only promote the proliferation, colony formation and migration of HCC cells, but also maintain tumor growth and metastasis by secreting hepatocyte growth factor (HGF)." (PMID 32863765, 2020). "All of these mechanisms are regulated by HGF secreted by tumor cells and MET expressed on tumor endothelial cells." (PMID 33066121, 2020). "TGFβ, FGF and hepatocyte growth factor (HGF) secreted by CAFs act on tumour cells, inducing epithelial‐mesenchymal transition (EMT) and a pre‐metastatic state." (PMID 32588948, 2020). "Neutrophils can secrete proinflammatory and immunoregulatory factors, such as neutrophil elastase, hepatocyte growth factor, and β2-integrins, which have paracrine effects on tumor biology." (PMID 32158466, 2020). "Hepatocyte growth factor (HGF) is produced mainly by fibroblasts in tumor microenvironment, and mediates various tumorigenic processes including cell proliferation, survival, invasion and angiogenesis, by acting on its specific receptor, Met." (PMID 32422991, 2020). "Hepatocyte growth factor (HGF)/MET proto-oncogene- dependent nitric oxide (NO) release by neutrophils suppresses tumor growth." (PMID 32595638, 2020). "Despite its role as MMP inhibitor, TIMP-1 exerts also its function in promoting tumor proliferation and regulating metastatic potential through hepatocyte growth factor (HGF) induced by HIF-1α." (PMID 32982967, 2020). "The Hepatocyte Growth Factor is a strong mitogenic factor and seems to play important role in tumor angiogenesis." (PMID 32607415, 2020). "Combined, the in vivo results showed that MACC1 is involved in the regulation of OS tumor growth via the MACC1/HGF/c-Met signaling axis and the regulation of angiogenesis." (PMID 33425885, 2020). "HGF plays a critical role in anti-apoptosis, anti-inflammation, and angiogenesis which influences the invasive growth of the tumor." (PMID 32499786, 2020). "Adipocytes and preadipocytes are known to secret hepatocyte growth factor (HGF), which, together with its receptor present on tumor cells (c-Met), forms a signaling pathway intensely correlated with proliferation, metastasis, and angiogenesis." (PMID 32120856, 2020). "Hepatocyte growth factor (HGF)/Met axis has been demonstrated to promote tumor growth and metastasis of HCC and high expression of Met has been shown to correlate with a significantly shorter five-year survival in HCC patients." (PMID 32650537, 2020). "This, along with neutrophil and macrophage-derived secretion tumor growth factors such as hepatocyte growth factor, IL-6, IL-8, and metalloproteases, the tumor microenvironment becomes stimulated." (PMID 33054830, 2020). "Here, levels of HGF and Follistatin differed between the tumor tissue when originating either from EAC or from ESCC." (PMID 32023907, 2020). "Slit/Robo signaling can downregulate MET signaling, thereby countering the effects of HGF–MET interactions on the tumor cells." (PMID 32670371, 2020). "The high levels of lactate produced by tumor cells can then induce an upregulation of HGF secretion from CAFs, with a mechanism dependent on the NF-κB pathway." (PMID 33291749, 2020).
tumor (continued). "An imbalance in HGF/c-Met signal transduction is a driving factor for cancers of the digestive system, and this promotes tumor growth, as well as its invasiveness and dissemination." (PMID 33195182, 2020). "The importance of curcumin’s ability to decrease HGF secretion by the MRC5 cells was confirmed following the creation of MRC5-HGF cells and their addition to the organotypic model, resulting in significantly decreased tumour cell invasion." (PMID 31963196, 2020). "HGF/c-MET signaling is positively involved in tumor development, especially in terms of cell invasion and metastasis." (PMID 33718111, 2020). "Of these, integrin α3 (also known as ITGA3, CD49c, and VLA-3 subunit alpha) is a 140 KDa protein thought to be involved in the hepatocyte growth factor (HGF)/c-Met signal pathway contributing to tumour progression." (PMID 31953437, 2020). "Studies using tumor cells have shown that MM cells secret the inhibitory factors for osteoblastogenesis, such as hepatocyte growth factor (HGF) and TNFα." (PMID 33374627, 2020). "The activation of c-MET by hepatocyte growth factor (HGF) worsen the malignant features of tumor cells which results in a higher rate of cells motility, proliferation, metastasis, and invasion." (PMID 32795296, 2020). "Hepatocyte stromal cells or HCC tumor cells can express and release HGF into the tumor microenvironment." (PMID 32117981, 2020). "In thyroid cancer (TC), the crosstalk between ncRNAs and HGF/c-Met axis has a significant effect on tumor growth and progression." (PMID 32083078, 2020). "The HSPG-mediated signaling activation of HGF released in the tumor microenvironment and of its receptor c-MET promotes ECM remodeling, inflammation, migration, angiogenesis, and invasion." (PMID 32916872, 2020). "The tumour in one case of an H3122/HGF xenograft treated with both metformin and alectinib disappeared in the fourth week." (PMID 32041944, 2020). "For another, HGF is confirmed as a major pathological player in tumor invasion and metastasis 27-29." (PMID 32206115, 2020). "The HGF/c-Met signaling pathway can regulate various tumor cellular processes including growth, invasion and metastasis." (PMID 33374386, 2020). "MET/HGF hyperactivation is also related to resistance to EGFR-TKIs (tyrosine kinase inhibitors); HGF promotes the clonal selection of c-MET amplified tumor subpopulations, which confers them substantial growth advantage and invasive potential." (PMID 32575417, 2020). "Some studies have demonstrated that the HGF/MET axis-activated downstream PI3K signaling pathway plays an important role in tumor resistance to MET inhibitors." (PMID 32435640, 2020). "While others expounded HGF was usually negatively correlated with patient survival and deemed a poor biomarker in tumor development, metastasis and recurrence." (PMID 32206115, 2020). "VEGFA/VEGFR2 signaling is a crucial downstream pathway of HGF/c-Met axis and plays a vital role in tumor angiogenesis." (PMID 32083078, 2020). "With regard to EMT, in tumours of mice treated with HGF antibody + c-MET inhibitor (Hi + Ci), expression of E-cadherin was increased, while the expression of vimentin was reduced indicating inhibition of EMT." (PMID 32203220, 2020). "HGF produced by PSCs within the primary tumour is neutralised by the neutralising antibody, depriving its receptor c-MET (on cancer cells and endothelial cells), of ligand binding." (PMID 32203220, 2020). "A variety of studies have reported that malignant ascites contain a lot of tumor-promoting molecules, including exosomes and inflammatory cytokines such as interleukin (IL)-6, IL-8, IL-10, hepatocyte growth factor (HGF), TGFβ." (PMID 32230983, 2020). "We found that the triple combination (HGF antibody + c-MET inhibitor + G) effectively reduced tumour volume and, more importantly, eliminated metastasis even at an advanced stage of the disease." (PMID 32203220, 2020).
tumor (continued). "Intriguingly, emerging evidence has revealed that, in addition to its conventional function as an oncogene, the HGF/MET axis stands at the crossroads of tumor autophagy, immunity, and microenvironment." (PMID 32435640, 2020). "We previously identified several key factors in mediating CAFs’ tumor-promoting properties in GC, including HGF, Lumican and IL-6." (PMID 31659258, 2020). "Since the HGF/MET signaling pathway plays a crucial role in tumor progression, the design of new antibodies and inhibitors considering different perspectives is of great value for improving the efficacy of MET-targeted drugs." (PMID 32435640, 2020). "Our findings indicate that PDT can promote tumor–stroma crosstalk by promoting HGF release from fibroblasts." (PMID 32485915, 2020). "When fused to target membranes, tumor-derived exosomes enable target cells to respond to hepatocyte growth factor (HGF)." (PMID 32555170, 2020). "Both HGF and CXCL12 (cytoplasm) expression by tumor cells were correlated to OS in univariable Cox regression analysis, and HGF remained significant in the multivariable analysis." (PMID 32188473, 2020). "In human cancers, neutrophils exert tumor-promoting functions by producing a variety of factors, including HGF, CCL17, BMP2, among others." (PMID 32903528, 2020). "A study has shown that HGF is a systemic cytokine that also comes from tumor stroma (paracrine mode)." (PMID 33195182, 2020). "Heterotypic 3D culture models comprising PDAC cell lines and HGF-secreting fibroblasts were established to recapitulate the activation of the HGF–MET signaling axis as a result of tumor–stroma interactions." (PMID 32485915, 2020). "Activation of the HGF/c-Met signaling pathway can significantly promote cell scattering, which is the basis of tumor metastasis." (PMID 31973231, 2020). "As a powerful mitogen, HGF stimulates mitotic division in glial cells, endothelial cells and in the tumor cells themselves, by binding to its MET receptor." (PMID 32607415, 2020). "A recent study showed that the HGF/Met pathway is also involved in tumor invasion, proliferation, and angiogenesis in HCC34,35." (PMID 32198380, 2020). "Using a liver metastasis mouse model with cecal ligation and puncture (CLP), expressions of HGF and the roles of the HGF/c-Met pathway in the progression of tumor cells were examined." (PMID 32630328, 2020). "This HGF neutralising antibody abrogated the crosstalk between stroma and tumour, resulting in reduced tumour size." (PMID 33271944, 2020). "The significant role that HGF/MET plays in tumor progression and metastasis has made it a prime therapeutic target in oncology." (PMID 33066121, 2020). "HGF at 40 ng/mL induced significant tumor cells migration leading to wound closure over 24 h treatment period for the NCI-H322M cells but it took 72 h for the A549 cells to close the wound." (PMID 32545325, 2020). "MiR-26a significantly impaired in vivo tumor angiogenesis by inhibiting VEGFA production through HGF/c-Met axis in HCC cells." (PMID 32083078, 2020). "HGF shows angiogenic properties, as it stimulates degradation of the endothelial basement membrane, but also due to activating tumor cells to secrete other growth factors." (PMID 32607415, 2020). "Further, autocrine production of pro-HGF by tumor cells is also observed in multiple tumors and HGF is essential for the crosstalk between tumor cells and stromal cells." (PMID 32626713, 2020). "A variety of cellular responses are activated by c-Met/HGF signaling and mediate critical physiological processes for tumor growth and metastasis in human cancers, including angiogenesis, cellular invasion, and morphogenic differentiation." (PMID 32752302, 2020). "Compared to Fut8+/+ mice, Fut8-/- mice show limited liver carcinogenesis and liver regeneration, indicating the essential role of glycosylation on HGF-c-Met signaling and tumor progression." (PMID 32626713, 2020).
tumor (continued). "ABT-700, derived from a mouse mAb 224G11, is capable of antagonizing MET signaling in both HGF-dependent and -independent manners and inhibits tumor growth driven by MET overexpression, amplification, or autocrine HGF stimulation." (PMID 32962738, 2020). "This suggests that MET constitutes a relevant requirement for neutrophils chemoattraction and cytotoxicity in order to trigger an anti-tumor local immune response, mainly through an HGF/MET-dependent cytotoxic nitric oxide release." (PMID 31547040, 2019). "Exogenous HGF significantly increased the growth and colony formation of tumour cells in the presence of sorafenib (HGF+Sor versus Sor, P < 0.001)." (PMID 31130723, 2019). "To investigate if HGF regulates recruitment of TAMs in tumour microenvironment, we initially performed Boyden chamber migration assays." (PMID 31130723, 2019). "We measured expression of HGF in keratinocytes, fibroblasts, skin and tumor sections from Tpl2−/− mice and found it to be significantly higher than WT controls." (PMID 30631034, 2019). "Studies have shown that malignant ascites serves as an important tumor microenvironment, which is enriched with tumor-promoting factors such as TGFβ, hepatocyte growth factor (HGF), IL-6, IL-8, IL-10, vascular endothelial growth factor (VEGF) and so on." (PMID 31405096, 2019). "In our studies, several tumor cell lines showed sensitivity to a c-Met inhibitor at high HGF concentrations (50 ng/mL)." (PMID 30719213, 2019). "The c-Met/HGF signaling pathway plays a significant role in tumor and endothelial cells where it acts as a potent pro-angiogenic trigger." (PMID 30909397, 2019). "Aberrant HGF/MET activation and/or expression result in an aggressive phenotype and is associated with tumor progression, metastatic potential, and poor survival in BC patients." (PMID 31072015, 2019). "In order to make a more direct comparison between the concentrations used in in vitro studies and the tumor microenvironment, our lab utilized a microdialysis model to sample the concentration of HGF within the tumor of a live mouse." (PMID 30719213, 2019). "Hepatocyte growth factor (HGF) secretion by surrounding stromal cells in co-culture supports tumor growth in the presence of BRAF inhibitors through activation of the MET receptor tyrosine kinase and downstream MAPK/Erk activation." (PMID 31058079, 2019). "They demonstrated that not only tumor cells, however also stroma (non-tumor compartment) contribute to the development of resistance to sunitinib therapy due to upregulated HGF expression in stroma cells of mesenchymal origin." (PMID 30909397, 2019). "Many of the adipokines e.g., leptin, adiponectin, estrogen, insulin-like growth factor-1 (IGF-1) and hepatocyte growth factor (HGF), IL-6, and resistin, promote tumor growth." (PMID 31468283, 2019). "The Met and its ligand, the hepatocyte growth factor (HGF), also caused the release of nitric oxide to eliminate the tumor cells in anti-tumor neutrophils." (PMID 31010242, 2019). "Tumor cells that both secrete HGF and express c-Met are referred to in this paper as autocrine-activated tumor cells." (PMID 30719213, 2019). "MET, the receptor for the stimulatory hepatocyte growth factor (HGF), has been shown to be associated with a worse prognosis for EAC when overexpressed in the tumor." (PMID 31561465, 2019). "Previous studies indicated that HGF exists as scHGF in normal tissues and that its processing into tcHGF occurs in injured tissues and the tumor microenvironment." (PMID 31212972, 2019). "An example of such a strategy targets the HGF-cMet signal using a neutralizing anti-HGF antibody or cMet inhibitor, demonstrating early signs of anti-tumor activity in a phase I clinical trial." (PMID 31547627, 2019). "Amplifications of VEGFA gene (found in 4% to 8% of HCCs) induce both neoangiogenesis and tumor proliferation owing to the recruitment and activation of macrophages, which release hepatocyte growth factor (HGF)." (PMID 31892230, 2019).